LNCOG (lncRNA osteogenesis associated)
Synonyms: RP11-54A9.1; lncRNA-OG; LINC02407
Gene: Long non-coding RNA gene on chromosome 12 (76,252,271 to 76,305,969, forward strand). Ensembl gene ENSG00000257219.
Diseases named in the same sentence as LNCOG in open-access papers:
LNCOG is named in the same sentence as 3 diseases in open-access papers, as found by Europe PMC text mining. Sharing a sentence is not in itself a finding about the gene and the disease.
LNCOG shares sentences with these, for which no sentence is quoted: cancer (2 papers); gastric cancer (1); tumor (1).